NOTCH2 (notch receptor 2)
Diseases named in the same sentence as NOTCH2 in open-access papers (continued):
Sharing a sentence is not in itself a finding about the gene and the disease.
marginal zone lymphoma (11 papers, 2011 to 2025). A usually indolent mature B-cell lymphoma, arising from the marginal zone of lymphoid tissues. "Mutations in the NOTCH pathway are related to marginal zone lymphoma, and NOTCH2 mutation can be found in up to 25% of patients with marginal zone lymphoma." (PMID 40283646, 2025). "Thus, Notch2 mutations were found to be highly penetrant and specific for marginal zone lymphomas, when compared to other B-cell leukemias and lymphomas." (PMID 33400727, 2020). "The frequency of NOTCH2 mutations in OAML is similar to other marginal zone lymphomas." (PMID 27566587, 2016). "The mutation pattern of the BN2/C1/NOTCH2 group, including mutation of NOTCH2, TNFAIP3, and BCL10 resembles that of marginal zone lymphomas (MZL) 52,53." (PMID 36788062, 2023). "Previous study of marginal zone lymphoma showed NOTCH signaling alterations, and we detected frequent NOTCH1 (4/35 = 11%) and NOTCH2 mutations (2/35 = 6%)." (PMID 34203889, 2021). "In fact, Notch2 is involved in the development of B1 and marginal zone B cells, and Notch2 is overexpressed in some marginal zone lymphomas (MZLs)." (PMID 22128846, 2011). "In addition, for cases with single BCL6-trans signature, the mutations in several genes were also frequently determined in marginal zone lymphoma, including NOTCH2 (14.6%, 6/41), KLF2 (34.1%, 14/41), TNFAIP3 (19.5%, 8/41), and FAS (17.1%, 7/41) mutations." (PMID 32736575, 2020). "The molecular characteristics of BN2, such as the NOTCH2 mutation and the BCL6 translocation, are shared by marginal zone lymphoma (MZL) and transformed MZL." (PMID 40507898, 2025).
osteoporosis (11 papers, 2013 to 2023). A condition of reduced bone mass, with decreased cortical thickness and a decrease in the number and size of the trabeculae of cancellous bone (but normal chemical composition), resulting in increased fracture incidence. "In turn, administration of Notch2 inhibitors rescued osteoporosis caused by FBXW7-deletion." (PMID 33572704, 2021). "Additionally, truncating mutations in the last exon of NOTCH2 can cause a rare skeletal disorder with osteoporosis." (PMID 23597238, 2013). "An antibody targeting the NRR of Notch2 was able to reverse osteoporosis in a murine Notch2 HCS model." (PMID 33572704, 2021). "In another study, heterozygous mutations in NOTCH2, such as the nonsense mutation c.7198C>T in HCS06 and mutation c.6383delG in HCS02, were identified as the cause of Hajdu–Cheney syndrome, which affects several organ systems, leading to severe osteoporosis and other abnormalities." (PMID 37728427, 2023).
renal fibrosis (10 papers, 2017 to 2025). A final common manifestation of a wide variety of chronic kidney diseases characterized by glomerulosclerosis and tubulointerstitial fibrosis. "To explore the precise role of macrophage‐derived Notch2 in the progression of sympathetic nerve activity‐associated renal fibrosis, we expressed the diphtheria toxin (DT) receptor in transgenic mice under control of the LysM promoter (LysMCre/Rosa26iDTRRosa26iGFP)." (PMID 40908548, 2025). "On the basis of our findings in vitro and in vivo, we here propose that the JNK/Notch-2 signaling axis is critically involved in TGF-β1-mediated renal fibrosis, and TSA treatment efficiently suppresses the JNK-dependent Notch-2 signaling pathway." (PMID 29101337, 2017). "In conclusion, data from our experiments demonstrate that upregulated Notch-2, at least for renal fibroblasts, plays a pivotal role in the pathological process of renal fibrosis." (PMID 29101337, 2017). "Pharmacological inhibition of different signaling pathways and genetic knockdown of Notch-2 further revealed JNK as an upstream effector of Notch-2 in TGF-β1-mediated renal fibrosis." (PMID 29101337, 2017). "Consistently, we also demonstrated that administration of TSA or a γ-secretase inhibitor RO4929097 in the mouse model of unilateral ureteral obstruction significantly ameliorated renal fibrosis through suppression of the JNK/Notch-2 signaling activation." (PMID 29101337, 2017). "The researchers implicated that CDKN2B-AS1 could putatively act as a sponge of miR-98-5p and increase the levels of its target protein notch homolog 2 (NOTCH2), which was an important regulator of renal fibrosis." (PMID 35517509, 2022). "A recent report showed that TSA might target JNK−dependent Notch-2 signaling to attenuate renal fibrosis." (PMID 34207271, 2021). "It is therefore possible that activation of Notch receptors, especially for Notch-1 and Notch-2, in the development and progression of renal fibrosis could be in a context-dependent, cell-type-specific manner." (PMID 29101337, 2017). "Thus, macrophages play a profibrotic role in kidney fibrosis, and macrophage‐derived Notch2 may act as a major contributor to the renal fibrosis." (PMID 40908548, 2025). "In a mouse model of renal fibrosis, the Notch2 signaling pathway was found to affect the metabolism of mouse kidney cells by regulating the expression of the mitochondrial transcription factor (ATfam), which in turn affects the development of renal fibrosis in mice." (PMID 40630953, 2025). "Notch homolog 2 (NOTCH2) is one of the important receptors in the NOTCH pathway, which also mediates renal fibrosis." (PMID 38390204, 2024).
splenic marginal zone lymphoma (10 papers, 2016 to 2023). Splenic marginal zone lymphoma is a rare, indolent B-cell non-Hodgkin lymphoma characterized by abnormal clonal proliferation of mature B-lymphocytes with involvement in the spleen, bone marrow and, frequently, the blood. "Consistently, NOTCH2 haploinsufficiency results in a severe reduction of splenic marginal zone B cells in Notch2+/f, CD19-Cre (Notch2+/−) mice models, while gain-of-function NOTCH2 mutations occur in 10–25% of splenic marginal zone lymphomas (SMZLs)." (PMID 33003595, 2020). "NOTCH2 is recurrently mutated across a spectrum of B cell malignancies including follicular lymphoma (FL), mantle cell lymphoma (MCL), splenic marginal zone lymphoma (SMZL), CLL, BL, and HL." (PMID 35844989, 2020).
mantle cell lymphoma (9 papers, 2018 to 2023). Mantle cell lymphoma is a rare form of malignant non-Hodgkin lymphoma affecting B lymphocytes in the lymph nodes in a region called the ``mantle zone''. "Similar NOTCH1 and NOTCH2 mutations have been seen in multiple B-cell malignancies including chronic lymphocytic leukaemia (CLL), mantle cell lymphoma (MCL), Hodgkin’s and Burkitt’s lymphomas, further supporting its role in these haematological malignancies." (PMID 32575680, 2020).
neuroblastoma (9 papers, 2017 to 2025). Neuroblastoma (NB) is the most common solid, extracranial childhood tumor. "Next, we detected that MOXD1, as well as the MES-associated PRRX1, SNAI2, and NOTCH2 genes were virtually restricted to the MES-like SH-EP cells by analyzing extracted RNA from five different conventional neuroblastoma cell lines." (PMID 38905335, 2024). "We conclude that MES-specific SEs are associated with NOTCH2 and MAML2 and that mesenchymal neuroblastoma cells have transcriptional activation and signaling of the NOTCH pathway." (PMID 30948783, 2019). "The specific inhibitor of MK APT-1 significantly reduced the volume and weight of neuroblastoma and also reduced the expression of the nuclear transcription factor HES1 in the Notch2 signaling pathway." (PMID 35774607, 2022). "Neuroblastoma-specific mesenchymal transcriptional signature was also repressed after BAF disruption in neuroblastoma cells, involving the epigenetic repression of key regulators of the mesenchymal phenotype, such as SNAI2, CDH11, CDH2, LOXL2 and NOTCH2." (PMID 36057593, 2022). "ChIP-sequencing analysis of H3K27ac revealed SEs8,9 within the gene bodies of NOTCH2 and MAML2 that were specific for MES-type neuroblastoma cells." (PMID 30948783, 2019). "The same super-enhancers of NOTCH2 and MAML2 were observed in neural crest cells, corroborating the idea that MES-type neuroblastoma cells are neural crest-like." (PMID 30948783, 2019). "RT-qPCR analysis of the three mammalian Notch receptors (Notch 1, Notch 2, and Notch 3) in SH-SY5Y, KELLY and IMR-32 neuroblastoma cell lines." (PMID 28525978, 2017). "Additionally, Notch2, one of the MK receptors, was found to contribute to neuroblastoma (NB) tumorigenesis through Notch-HES1 signaling in an MK-deficient MYCN transgenic mice model for NB." (PMID 37835544, 2023).
pulmonary fibrosis (9 papers, 2021 to 2026). Chronic progressive interstitial lung disorder characterized by the replacement of the lung tissue by connective tissue, leading to progressive dyspnea, respiratory failure, or right heart failure. "Critical to their pro-fibrotic capacity, Notch2 signaling directs their differentiation into a specialized macrophage lineage implicated in pulmonary fibrosis." (PMID 40650314, 2025). "Taken together, our study demonstrated that SNHG16 promoted pulmonary fibrosis by targeting miR-455-3p to regulate the Notch2 pathway." (PMID 33549106, 2021). "This indicates that MDK may promote lung fibrosis by interacting with Notch2 and activating angiotensin-converting enzyme (ACE) expression." (PMID 38075691, 2023). "Our data indicated that lncRNA SNHG16 could promote pulmonary fibrosis by targeting miR-455-3p to regulate the Notch2 pathway." (PMID 33549106, 2021). "Notch 2 had been reported to be enrolled in epithelium-mesothelium transition (EMT) and chemoresistance of pancreatic carcinoma, and participated in the process the pulmonary fibrosis in ARDS." (PMID 33639987, 2021). "In conclusion, the data presented here identified lncRNA‐ATB as an essential determinant of TGF‐β1‐induced EMT and silica‐induced pulmonary fibrosis and ascribed its pro‐fibrotic effect to the regulation of MEKK2 and NOTCH2 signalling pathways via sponging miR‐29b‐2‐5p and miR‐34c‐3p." (PMID 34180127, 2021). "MK activates the Notch2 signaling pathway, up-regulates the downstream target HES1 and promotes tumor cell proliferation while inhibiting tumor cell apoptosis Notch signaling has been found to be upregulated in pulmonary fibrosis, and inhibition of Notch significantly alleviated pulmonary fibrosis." (PMID 35774607, 2022).
asthma (8 papers, 2014 to 2025). "Midkine has also been implicated in another airway disease, COPD, in which the midkine‐Notch2 axis drives ASMC proliferation and remodeling, suggesting shared pathogenic mechanisms between COPD and asthma." (PMID 40969143, 2025). "Research findings using rat models of asthma demonstrated that the presence of Notch1 and Notch2 on CD4+ T cells, along with Jagged1 on dendritic cells and/or Dll1 on smooth muscle cells, facilitated asthma development." (PMID 39450276, 2024). "In the OVA‐induced asthma mice model, Notch1, Notch2 and Notch3 were all highly expressed in the lung tissues." (PMID 32935466, 2020). "In this study, we demonstrated in vivo that Notch1 and Notch2 were indeed playing a positive role in asthma, but the effect of Notch2 was much lower than Notch1." (PMID 24706026, 2014). "Of note, Notch1, Notch2 and Notch3 are strongly overexpressed in the lung tissues of rats with ovalbumin‐induced asthma, and Notch1 inhibition by emodin treatment confers more remarkable transformations within the lung tissue than does Notch2 and Notch3 inhibition." (PMID 35355403, 2022).
brain tumor (8 papers, 2007 to 2022). "Notch2 has been suggested to drive embryonic brain tumor growth, whereas Notch3 has been implicated in choroid plexus tumors." (PMID 21078177, 2010). "As a consequence of local genomic amplifications at the Notch2 locus in both brain tumor types, this may also be linked to the later persistence of Notch2 expression in postnatal mouse brain." (PMID 21078177, 2010). "NOTCH2 is a component of the Notch pathway that acts as a mitogen for cerebellar granule cell precursors and whose expression has been associated with malignancy in brain tumors and with the persistence of cancer cells." (PMID 18826648, 2008). "Notch2 has been known to drive embryonic brain tumor growth and genesis of GBM, playing a role in proliferation, differentiation and apoptosis." (PMID 30606241, 2019). "Additionally, it has been shown that Notch-1 and Notch-2 exert opposite regulatory effects on the growth of embryonic brain tumors." (PMID 32993109, 2020).
colon carcinoma (8 papers, 2011 to 2025). "EGCG inhibited Notch-2 in colon cancer cell line, and nearly ablated Hes-1 gene expression in colon cancer cells, suggesting pathway deactivation." (PMID 35408894, 2022). "More specifically, we suggest that Notch-2 is a noveltarget, activated by Wnt signaling in colon cancer cells." (PMID 21437251, 2011). "Down-regulation of Notch2 signaling in intestinal epithelial cells leads to impaired DC differentiation ability, a reduced number of mature DCs and reduced antigen presentation ability, which promotes the development of colon cancer." (PMID 36713833, 2023). "Similarly, the overexpression of miR-195-5p and miR-139-5p sensitized colon cancer cells to 5-FU through decreased expression of Notch2/RBP-jκ and Notch1, respectively." (PMID 34680255, 2021). "The NOTCH2 gene encodes a transmembrane protein which physically associates with active beta catenin and decreases its levels leading to lower WNT activity in both stem and colon cancer cells." (PMID 27551309, 2016). "In addition, miR-34a has an inhibitory effect on NOTCH1, NOTCH2, and NOTCH4 expression in pancreatic ductal carcinoma, whereas, in colon carcinoma, its inhibition rescued the expression of NOTCH1, NOTCH2, and BCL2." (PMID 40149537, 2025). "Additionally, colon cancer resistance to oxaliplatin could be related to the upregulation of JMJD3 and UTX, decreasing the tri-methylation of H3K27 at Notch2 gene and permitting its transcription, whereas the addition of GSK-J4 notably potentiated platinum-drug induced apoptosis." (PMID 34680255, 2021).
liver fibrosis (8 papers, 2012 to 2024). "Since the genes of Smad4, Jun, Ctnnb1, and Smad5 have been reported to be associated with liver fibrosis, and the Notch2 gene was considered to be related to Wnt and TGF-β signaling pathways, these five candidate target genes were selected for research." (PMID 35883205, 2022). "Consistent with experiments in vitro, with the decrease of the profibrotic markers including α-SMA and Col1α1, a significantly lower expression level of Notch2 was found in hepatic fibrosis mice transplanted with HUC-MSCs compared with the BDL control group." (PMID 35883205, 2022). "Taken together, these results indicated that HUC-MSCs alleviated hepatic fibrosis through up-regulating miR-148-5p by targeting Notch2 and suppressing the Notch signaling pathway." (PMID 35883205, 2022). "Expressions of Notch2, Notch3, and Notch target gene Hes1 were significantly up-regulated during the development of hepatic fibrosis." (PMID 35883205, 2022). "In addition to genetic manipulation, we have investigated the effect of antibodies against NOTCH1 and NOTCH2 on the development of liver fibrosis." (PMID 39529885, 2024). "In addition to genetic manipulation, we investigated the effect of antibodies against NOTCH1 and NOTCH2 on the development of liver fibrosis." (PMID 39529885, 2024). "MiR-29a-3p2 increases liver fibrosis and stimulates liver stellate cells by modulating NOTCH2." (PMID 35322757, 2022). "The down-regulation of miR-148-5p and up-regulation of Notch2 could be used as biomarkers to monitor the progression of liver fibrosis." (PMID 35883205, 2022). "In the CCl4-induced liver fibrosis rat experiment, qPCR showed that the mRNA expressions of Jagged1, Jagged2, Notch2, Notch3, Notch4 and recombination signal binding protein-κB (RBP-κB) were significantly more upregulated in the CCl4 group than those in the control group." (PMID 34630075, 2021). "In addition, we also observed that lnc-LFAR1 promotes hepatic fibrosis by activating Notch signaling in vitro and in vivo, as demonstrated by an increased expression of the Notch receptors, Notch2 and Notch3, and Notch target gene Hes1." (PMID 28747678, 2017). "Furthermore, the effects of inhibitory antibodies against NOTCH1 or NOTCH2 might be effective in other models of liver fibrosis." (PMID 39529885, 2024). "In this study, the expressions of Jagged1, Jagged2, Notch2, Notch3, Notch4, and RBP-κB were significantly increased in CCl4-and BDL-induced liver fibrosis in rats and mice." (PMID 34630075, 2021). "Consistent with the CCl4-induced rat liver fibrosis model, JY5 decreased the expressions of Jagged1, Notch2, Notch3, Notch4 and RBP-κB in the BDL-induced liver fibrosis model." (PMID 34630075, 2021). "While in CCl4-induced liver fibrosis mice experiment, JY5 not only decreased the mRNA expressions of Jagged1, Notch2, Notch3, Notch4 and RBP-κB, but also downregulated the expression of Dll1." (PMID 34630075, 2021). "The levels of expression of Notch1-ICD and Notch2-ICD proteins did not change significantly during liver fibrosis, as indicated by Western blot analysis." (PMID 23056328, 2012). "However, treatment with either anti-NOTCH1 or anti-NOTCH2 antibodies did not change the degree of liver fibrosis in either CCl4 or in DDC-model." (PMID 39529885, 2024).
esophageal cancer (7 papers, 2021 to 2023). A primary or metastatic malignant neoplasm involving the esophagus. "However, DTX3 plays a contradictory role in the progression of esophageal cancer, during which it suppresses tumorigenesis by promoting the ubiquitination and degradation of NOTCH2, a key protein implicated in cell proliferation and cell-fate determination." (PMID 35098394, 2022). "In accordance with that, we showed the mutation frequencies of NOTCH1 and NOTCH2 genes in esophageal mucosa of our patients (median age: 66 years, range: 49-75 years), most of whom have smoking and drinking history, were significantly higher than those in esophageal carcinoma." (PMID 35515115, 2022). "Recently, however, it has been found to physically interact with Notch2 by Yeast-Two-Hybrid assay and to inhibit Notch2-mediated proliferation in esophageal carcinoma." (PMID 37108544, 2023). "It was reported that the expression of DTX3, acted as an anti-oncogene, was negatively correlated with NOTCH2 and suppressed proliferation and tumorigenicity of human esophageal carcinoma cells." (PMID 33403043, 2021). "In a recent study of oesophageal cancer, DTX3 was found to increase degradation of NOTCH2 and reduce proliferation and migration of oesophageal cancer cells." (PMID 33616774, 2021).